INS (insulin)
Diseases named in the same sentence as INS in open-access papers (continued):
Sharing a sentence is not in itself a finding about the gene and the disease.
type 1 diabetes (continued). "Type I diabetes mellitus is an autoimmune disease characterized by local inflammatory reaction in and around islets that is followed by selective destruction of insulin secreting β-cell and it occurs mainly in childhood." (PMID 27579151, 2016). "Future exercise studies in type 1 diabetes following insulin delivery adjustments should include evaluation of blood glucose levels over longer periods post-exercise since delayed hypoglycaemia, particularly overnight, remains a clinical concern." (PMID 27287376, 2016). "Type 1 diabetes is an autoimmune disorder in which the insulin-producing cells of the pancreas are destroyed, resulting in a requirement for exogenous insulin for survival." (PMID 26492518, 2016). "In conclusion, insulin-dependent diabetes altered the normal rhythmicity of the cornea, and insulin administration had a beneficial effect on restoring normal rhythmicity in the diabetic cornea." (PMID 27611469, 2016). "However one should keep in mind that type 1 diabetic patients are usually treated with insulin, which basically normalizes the metabolic derangements induced by insulin deficiency and may thus attenuate the true detrimental effects of type 1 diabetes on the heart." (PMID 27999359, 2016). "Improved insulin sensitivity following muscle glycogen depletion can also lead to nocturnal hypoglycemia in people with type 1 diabetes." (PMID 27073714, 2016). "The patients with type 1 diabetes often have to regularly inject insulin which help to control their blood sugar." (PMID 27535125, 2016). "Long-acting insulin analogues for type 1 diabetes (T1D) treatment have been available on the Brazilian market since 2002." (PMID 27907034, 2016). "Type I diabetes is an autoimmune disease which results the destruction of the insulin-secreting cells, beta cells." (PMID 26752052, 2016). "The current treatment approach for type 1 diabetes is based on daily insulin injections, combined with blood glucose monitoring." (PMID 27400873, 2016). "Modeling the G/I system is particularly relevant nowadays in the therapeutic area of type 1 diabetes (T1D), specifically in those patients treated with continuous subcutaneous insulin infusions (CSII) coupled with continuous glucose monitoring (CGM)." (PMID 27824066, 2016). "For instance, camel milk was proposed as an adjunct to insulin-based therapy allowing the reduction of insulin doses required in patients with type 1 diabetes." (PMID 26858689, 2016). "Insulin requirements vary considerably within individuals with type 1 diabetes by on average 30% overnight and 20% during waking hours." (PMID 27364997, 2016). "Technological advances pertaining to the use of closed-loop systems in conjunction with insulin pump therapy for type 1 diabetes are evolving." (PMID 26742082, 2016). "Type 1 diabetes (T1D) is an autoimmune disease characterized by destruction of the insulin-secreting islets of Langerhans, resulting in hyperglycemia." (PMID 26900470, 2016). "Insulin therapy has been used to treat type 1 diabetes patients since the discovery of insulin in 1922." (PMID 28191438, 2016). "Islets of Langerhans isolated from deceased donor pancreata are currently transplanted in Type 1 diabetes patients who can then optimally achieve insulin-independence for long periods." (PMID 26987985, 2016). "Type 1 diabetes (T1D) is a T cell-mediated autoimmune disease in which insulin-producing β cells of the pancreatic islets of Langerhans are selectively destroyed." (PMID 27790217, 2016). "The studies provided 3278 patient-years of exposure to BIL and 2016 patient-years of exposure to comparator insulins in three patient groups: type 1 diabetes, type 2 diabetes on a basal-bolus regimen, and type 2 diabetes on basal insulin only." (PMID 27188479, 2016). "Insulin pump therapy, considered the most physiological form of insulin replacement for type 1 diabetes allows modulation of basal insulin delivery before, during and after exercise." (PMID 27287376, 2016).
type 1 diabetes (continued). "Type 1 Diabetes (T1D) is characterized by pancreatic beta cell destruction and the inability to produce insulin and maintain glycemic control." (PMID 27197730, 2016). "Type-1 diabetes is also referred to as insulin-dependent diabetes because patients need to take insulin injections for the rest of their life." (PMID 27916864, 2016). "In contrast, of the 9 individuals assigned “possible” type 1 diabetes, 22% (2/9) had a C10E code in primary care, and only 11% (1/9) were on insulin only." (PMID 27631769, 2016). "Children and adolescents with type 1 diabetes using modern intensive insulin treatment had echocardiographic signs of reduced diastolic myocardial function despite short duration of disease." (PMID 27225446, 2016). "We investigated the potential of empagliflozin to recover insulin pathways in type 1 diabetes by improving pancreatic β-cell mass." (PMID 26807719, 2016). "Type 1 diabetes is an autoimmune disease in which insulin-producing pancreatic islet β cells are the target of self-reactive B and T cells." (PMID 27069933, 2016). "The current standard of care in type 1 diabetes is flexible intensive insulin therapy, which should lead to the achievement of correct metabolic balance and good quality of life." (PMID 28090541, 2016). "The mainstay of treatment for Type 1 Diabetes is exogenous insulin using a combination of basal and bolus insulin." (PMID 27777901, 2016). "Methanol extracts from E. cava containing high levels of polyphenol and strong ROS scavenging ability significantly reduced blood glucose levels and increased insulin concentration when fed to type-1 diabetic rats." (PMID 26999166, 2016). "We aimed to assess the changes in glycemic control and insulin doses in a group of children and adolescents living with type 1 diabetes in Cameroon during and after camp attendance." (PMID 26791079, 2016). "Type 1 diabetes (T1D) is characterized by a chronic, progressive autoimmune attack against pancreas-specific antigens, effecting the destruction of insulin-producing β-cells." (PMID 27708334, 2016). "Over the last 15 years, CSII has increasingly been used in adults and children in an effort to optimise insulin delivery in type 1 diabetes." (PMID 27050468, 2016). "Rodent models of type 1 diabetes (T1DM) also display significant MAT accumulation, providing a second example of perturbed insulin signaling associating with hyperlipidemia and MAT expansion." (PMID 27445989, 2016). "Possible screenings for the more severe type-1 diabetes consist in identifying molecules able to protect pancreatic β cells (which produce insulin), by reducing inflammation and oxidative processes." (PMID 27916864, 2016). "We aimed to characterize insulin responses to i.v. glucose during the preclinical period of type 1 diabetes starting from the emergence of islet autoimmunity." (PMID 26620391, 2016). "Plasma insulin was reduced by CaBP-9k ablation, suggesting that CaBP-9k KO mice are closer to the model of Type 1 diabetes than T2D." (PMID 27736926, 2016). "As a result, patients with type 1 diabetes ultimately become reliant on the lifelong administration of external insulin." (PMID 28082906, 2016). "To conclude, our study demonstrates that the insulin secretory capacity of the β-cells is compromised early during the disease process leading to type 1 diabetes." (PMID 26620391, 2016). "Insulin treatment mimics endogenous insulin secretion imperfectly, thereby exposing individuals with type 1 diabetes to a hyperinsulinaemic environment." (PMID 27011769, 2016). "Nearly 90 % of individuals with type 1 diabetes have presence of one or more islet autoantibodies such as insulin (IAA), glutamic acid decarboxylase (GADA), insulinoma-associated autoantigen 2 (IA-2), and zinc transporter 8 (ZnT8A)." (PMID 28702252, 2016).
type 1 diabetes (continued). "It is widely accepted that type 1 diabetes mellitus (T1DM) is an autoimmune disease that is characterized by the destruction of pancreatic β-cells, which causes an absolute deficiency of insulin secretion." (PMID 26639354, 2016). "Type 1 diabetes is also known as juvenile diabetes or insulin-dependent diabetes as the patients’ pancreas cannot produce or produces little insulin and often presents itself from childhood (Diabetes.co.uk, 2016c)." (PMID 27729921, 2016). "As patients aged ≥35 years who were treated with insulin from diagnosis had the highest rate of misclassification (56% classed incorrectly as having type 1 diabetes), further investigation should be considered in this subgroup." (PMID 27080317, 2016). "One of these PEPs was glycated haemoglobin (HbA1c) in type 1 diabetes (insulin degludec), which was explicitly specified by the G-BA as a validated and patient-relevant endpoint." (PMID 27842592, 2016). "We aim to evaluate the frequency of DD in a real-world type 1 diabetes sample and the interaction of insulin treatment with CVRF." (PMID 27011769, 2016). "Type 1 diabetes is an autoimmune process that completely destroys the insulin-producing pancreatic beta cells, leaving the individuals dependent on exogenous insulin." (PMID 27170498, 2016). "Supplementation with DJC resulted in a significant amelioration of type 1 diabetes as manifested by reduced blood glucose, increased fasting plasma insulin and improved body weight gains." (PMID 26819084, 2016). "In people with type 1 diabetes, insufficient insulin prevents the body from getting glucose from the blood into the body’s cells to use as energy." (PMID 27625707, 2016). "In type 1 diabetes, restoration of normoglycemia can be achieved if the autoimmune attack on beta cells ceases and insulin requirement is met by the residual beta cells." (PMID 27874076, 2016). "Type 1 diabetes (T1D) is characterized by permanent destruction of insulin‐producing beta cells in the pancreatic islets." (PMID 26565566, 2016). "Preclinical tolerizing therapy protocols in the NOD model have showed that insulin is a primary autoantigen and initiates type 1 diabetes." (PMID 27069933, 2016). "Transplantation of insulin-producing cells derived from the patients themselves would be one of the most promising approaches to cure type 1 diabetes." (PMID 27662374, 2016). "Most patients who were misclassified as having type 1 diabetes were diagnosed aged ≥35 years, and were given insulin immediately." (PMID 27080317, 2016). "The HR for MACE+ for patients with type 1 diabetes (integrated results of two studies) for treatment with BIL versus comparator insulin was 0.24 [95 % CI: 0.07–0.85], nominal p = 0.027." (PMID 27188479, 2016). "Clinical trials performed in diabetic patients have demonstrated that in type 1 diabetes, long-term oral vanadium consumption alongside with the reduction of high blood glucose lowers the required dose of daily insulin." (PMID 26459400, 2016). "Multiple human trials on fenugreek seeds also demonstrate potential efficacy in lowering total cholesterol in people with moderate atherosclerosis or insulin- or non-insulin-dependent diabetes." (PMID 27733237, 2016). "Type 1 diabetes (T1D) is preceded by a lengthy subclinical period during which the insulin-producing pancreatic beta cells are destroyed by an autoimmune process." (PMID 27391588, 2016). "Type 1 diabetes develops when the insulin-secreting beta cells are destroyed by infiltrating T cells." (PMID 26911290, 2016). "Various studies with human patients have shown that treatment of Type 1 diabetes with p277 epitope can preserve part of the endogenous insulin production by arresting the destruction of the β-cell mass in the pancreas." (PMID 27478851, 2016). "Five basic elements are applied in the treatment of type 1 diabetes: insulin, diet, self-control, exercise, and education." (PMID 28090541, 2016).
type 1 diabetes (continued). "In patients with insulin-dependent diabetes, to deliver appropriate amount of insulin to the liver and achieve good metabolic control, most often supraphysiological doses of insulin are injected subcutaneously." (PMID 27239195, 2016). "In type 1 diabetes (T1D), circulating, pancreas-specific autoantibodies are correlated with the onset of a chronic, pancreatic autoimmune attack leading to the progressive loss of insulin-producing β-cells." (PMID 27708334, 2016). "Patch insulin infusion pumps are a relatively recent innovation aiming to increase CSII compliance for insulin-dependent diabetes patients." (PMID 29632592, 2016). "Insulin pump therapy is widely considered to be the most physiological form of insulin replacement for people with type 1 diabetes." (PMID 27287376, 2016). "Type 1 diabetes, which is the chronic autoimmune disease, results from the destruction of the insulin-producing β-cell of the pancreas, leading to a gradual decrease in β-cell mass." (PMID 26888412, 2016). "During a 5-day camp, we collected data on insulin doses, HbA1c, weight and blood glucose at least six times per day in a group of children and adolescents living with type 1 diabetes." (PMID 26791079, 2016). "C-peptide has been mainly used to assess the presence of an insulin-dependent state for the diagnosis of type 1 diabetes." (PMID 27196896, 2016). "Streptozotocin (STZ)-treated mice are a model of Type 1 diabetes, as STZ treatment is toxic to the beta-cells of the pancreas, rendering STZ-treated mice insulin deficient." (PMID 25849138, 2015). "Our findings indicate that these data improved the identification of type 1 diabetes in insulin users." (PMID 25621692, 2015). "We use this methodology to study four parameters relating to insulin kinetics in pregnant women with type 1 diabetes, using data from two clinical studies." (PMID 26013427, 2015). "Nevertheless, in animal models have been demonstrated that MSCs can revert type I diabetes, enhances insulin secretion and sustain normoglycemia." (PMID 25961059, 2015). "Type I diabetes mellitus results from the autoimmune destruction of the insulin-producing cells in the pancreas." (PMID 26062681, 2015). "This is the first study to evaluate the use of professional CGM for the identification of type 1 diabetes in diabetic subjects receiving insulin therapy." (PMID 25621692, 2015). "As a result, individuals with type 1 diabetes must inject insulin to help their bodies process sugars." (PMID 26061776, 2015). "Hypoglycemia is the main side effect of intensified insulin therapy in type 1 diabetes and recognized as a limitation in achieving glycemic targets." (PMID 26292721, 2015). "Insulin administration, as the standard treatment strategy for type 1 diabetes, cannot exactly mimic the physiologic secretion of insulin in the body." (PMID 26576437, 2015). "Such combined effect has not been documented with any other means of intensified conventional insulin delivery in type 1 diabetes." (PMID 25492378, 2015). "Early research in the 1980s confirmed this relationship between CHO and insulin therapy in type 1 diabetes using an artificial pancreas." (PMID 26202844, 2015). "In this paper, a decision support tool is presented for setting insulin therapy in new-onset type 1 diabetes." (PMID 25888901, 2015). "Type 1 diabetes (T1D) is a complex, multigenetic autoimmune disease featured by destruction of the insulin producing beta-cells of the pancreas by autoreactive T lymphocytes." (PMID 26249556, 2015). "In the present study, we recruited only participants with type 1 diabetes whose serum C-peptide level was below the limit of detection, given that the pharmacology of basal insulin is well reflected by the plasma glucose level in such individuals." (PMID 26044206, 2015). "Type 1 diabetes (T1D) is a chronic autoimmune disorder, characterized by autoreactive T cell-mediated destruction of insulin-producing β-cells in the pancreatic islets of Langerhans1." (PMID 26279095, 2015).
type 1 diabetes (continued). "Type 1 diabetes is characterised by destruction of pancreatic beta cells by autoimmune processes leading to an absolute requirement for insulin replacement." (PMID 25810037, 2015). "The subjects were 22 type 1 diabetes patients treated with basal-bolus insulin regimen with twice-daily basal insulin." (PMID 26435713, 2015). "Overnight closed‐loop insulin therapy at home in adults and adolescents with type 1 diabetes is feasible, showing improvements in glucose control and reducing the risk of nocturnal hypoglycaemia." (PMID 25492378, 2015). "Type I diabetes (T1D) is a disorder of insulin production, resulting from the destruction of pancreatic beta-cells by auto-reactive T cells." (PMID 26020954, 2015). "Two female patients with type 1 diabetes who began treatment with CSII required to increase their previous breakfast insulin-to-carbohydrate ratio in order to achieve postprandial glycemic goals." (PMID 25614824, 2015). "In a type 1 diabetes model, combination of allogeneic MSCs and sex-mismatched bone marrow cells resulted in normalization of blood glucose and serum insulin levels by T cells suppression." (PMID 26576437, 2015). "In type 1 diabetic patients, who have lost their ability to produce insulin, transplantation of pancreatic islet cells can normalize metabolic control in a manner that is not achievable with exogenous insulin." (PMID 25889474, 2015). "A primary focus of the management of type 1 diabetes has been on matching prandial insulin therapy with carbohydrate amount consumed." (PMID 26202844, 2015). "Linkage of CTB to insulin (CTB-INS) provided a protective effect against the onset of type 1 diabetes in NOD mice." (PMID 26378585, 2015). "Unfortunately, many patients with type 1 diabetes cannot achieve the target glycemic control, and insulin therapy leaves room for improvement." (PMID 26435713, 2015). "It has been found that ROS overproduction can directly lead to pancreatic β-cell dysfunction and consequently result in the impairment of insulin secretion in Type 1 diabetes." (PMID 25452774, 2015). "Type 1 diabetes (T1D) is a chronic autoimmune disease in which insulin-producing pancreatic islet β cells are targeted and destroyed by autoreactive immune cells." (PMID 26579520, 2015). "Professional continuous glucose monitoring is a useful tool that improves identification of type 1 diabetes among diabetic patients receiving insulin therapy." (PMID 25621692, 2015). "Data concerning leptin levels in this group of patients vary, and exogenous insulin therapy leads to elevated leptin levels in patients with type 1 diabetes." (PMID 26273677, 2015). "The primary endpoints of this study were the SD and CV of FPG during treatment with IDeg and IGlar in a randomised crossover trial in individuals with type 1 diabetes who underwent basal-bolus insulin therapy." (PMID 26044206, 2015). "But most cases of type 1 diabetes are thought to result from selective destruction of insulin-producing β-cells in the islets of Langerhans." (PMID 25793188, 2015). "This remains the most common form of insulin therapy for type 1 diabetes; however, insulin pump therapy (IPT) is becoming an increasingly popular form of therapy." (PMID 26202844, 2015). "We recently reported improved glycemic control with reduced insulin dose in subjects with type 1 diabetes treated with the sodium glucose co-transporter-2 inhibitor empagliflozin." (PMID 26544192, 2015). "The proportion of basal to total insulin use during CSII therapy was lower in this Taiwanese sample of children with type 1 diabetes by comparison with that reported for Western samples." (PMID 25802842, 2015). "In two animal models of insulin deficiency (type I diabetes and fasting), liver ERBB3 expression is repressed following insulin treatment, suggesting an interaction between insulin and the NRG1/ERBB pathway." (PMID 26230680, 2015).